MED28 (mediator complex subunit 28)
Description:
Component of the Mediator complex, a coactivator involved in the regulated transcription of nearly all RNA polymerase II-dependent genes. Mediator functions as a bridge to convey information from gene-specific regulatory proteins to the basal RNA polymerase II transcription machinery. Mediator is recruited to promoters by direct interactions with regulatory proteins and serves as a scaffold for the assembly of a functional preinitiation complex with RNA polymerase II and the general transcription factors. May be part of a complex containing NF2/merlin that participates in cellular signaling to the actin cytoskeleton downstream of tyrosine kinase signaling pathways.
Synonyms: Magicin; EG1; DKFZP434N185; 1500003D12Rik
Tractability: Small molecule: a structure with a bound ligand is known. Antibody: UniProt places it where antibodies can reach, with high confidence. PROTAC: ubiquitination databases record sites on it.
Gene: Protein-coding gene on chromosome 4 (17,614,641 to 17,634,105, forward strand). Ensembl gene ENSG00000118579.
Subcellular location: Nucleus; Cytoplasm; Membrane
Subcellular location (Human Protein Atlas): Nucleoplasm
Pathways (Reactome):
Developmental Biology: Transcriptional regulation of white adipocyte differentiation
Disease: RSV-host interactions
Metabolism: PPARA activates gene expression
Gene Ontology:
Molecular function: protein binding
Biological process: positive regulation of transcription elongation by RNA polymerase II; positive regulation of transcription initiation by RNA polymerase II; RNA polymerase II preinitiation complex assembly
Cellular component: core mediator complex; nucleoplasm; nucleus; mediator complex; cortical actin cytoskeleton; cytoplasm; cytoskeleton; membrane
Genetic constraint (gnomAD): Loss-of-function variants: 21 observed, 17.53 expected, observed/expected ratio (o/e) 1.2, 90% interval 0.85 to 1.7. The upper end of that interval is the gene's LOEUF score, 1.7, which puts it in group 6 of 6, group 1 being the genes least tolerant of losing a copy. Missense variants: 242 observed, 214.03 expected, observed/expected ratio (o/e) 1.13, 90% interval 1.02 to 1.26. Synonymous variants: 108 observed, 89.05 expected, observed/expected ratio (o/e) 1.21, 90% interval 1.04 to 1.42.
Homologues: Orthologues: chimpanzee MED28 (100% identical), macaque MED28 (99% identical), rat Med28 (95% identical), mouse Med28 (94% identical), guinea pig MED28 (93% identical), dog MED28 (92% identical), pig MED28 (89% identical), tropical clawed frog med28 (78% identical), zebrafish med28 (77% identical), tropical clawed frog med28 (55% identical), Drosophila melanogaster MED28 (34% identical).
Diseases named in the same sentence as MED28 in open-access papers:
MED28 is named in the same sentence as 24 diseases in open-access papers, as found by Europe PMC text mining. Sharing a sentence is not in itself a finding about the gene and the disease. The quoted sentences say what the papers report.
breast carcinoma (7 papers, 2010 to 2023). "Elevated MED28 expression was associated with poor outcome in breast cancer patients, and targeted downregulation of MED28, either by siRNA or antibody, caused decreased breast cancer cell proliferation and reduced xenograft growth." (PMID 26445504, 2015). "Here we examined the association of MED28 expression with human breast cancer progression." (PMID 20584319, 2010). "Of note, an in vitro drug resistance model that is based on a breast cancer cell line has been reported to manifest enhanced expression of MED28, which regulates epithelial–mesenchymal transition in human breast cancer." (PMID 30970566, 2019). "MED28 was independently identified as a differentially expressed gene in endothelial cells and named endothelial-derived gene 1 (EG–1), with elevated expression in cancerous epithelial cells including carcinomas of the breast, colon and prostate." (PMID 26445504, 2015). "Our findings show that MED28 expression is a significant independent predictor of survival in women with both early and late stage breast cancer." (PMID 20584319, 2010). "Here we examine the expression levels of MED28 on a population basis using a human breast cancer tissue microarray (TMA)." (PMID 20584319, 2010). "To start testing this, we examined the expression of MED28 in a population of women with breast cancer using high-throughput TMA technology." (PMID 20584319, 2010). "This confirms and validates previous findings showing enhanced expression of MED28 in breast cancer." (PMID 20584319, 2010). "The presence of MED28 has been shown to increase cellular proliferation in both cell culture and mouse xenograft models using human breast cancer cells." (PMID 20584319, 2010). "The present study shows that the expression of MED28 is relatively higher in both early and advanced breast cancer lesions." (PMID 20584319, 2010). "Expression of MED28 protein was determined on a population basis using a high-density tissue microarray consisting of 210 breast cancer patients." (PMID 20584319, 2010). "A recently identified marker, MED28 (also known as EG-1 or magicin), has been found to be increased in breast cancer and may play a role in the progression of the disease." (PMID 20584319, 2010). "We have demonstrated that MED28 expression is increased in breast cancer." (PMID 20584319, 2010). "Previously, expression of MED28 was found to promote proliferation in breast cancer cells." (PMID 20584319, 2010). "Although the molecular mechanisms underlying MED28-mediated oncogenesis are unknown, previous studies have suggested that MED28 can increase cancer cell proliferation, and phenotypes that are related to the dysregulation of MED28 have been demonstrated in breast cancer cells." (PMID 30970566, 2019). "However, cancer genomics data, where MED28 was found to be amplified in various cancers, including breast cancer, ovarian cancer, pancreatic cancer, sarcoma, lung adenoma, prostate cancer, and melanoma, clearly indicate that the overexpression of MED28 is closely related to cancer progression." (PMID 30970566, 2019). "Recently, we have reported that MED28 appears involved in Wnt/β-catenin signaling in human colorectal cancer cells as well as EMT and migration in human breast cancer cells." (PMID 36072467, 2022). "Previously we found a link of MED28 with Wnt/β-catenin signaling in human colorectal cancer cells and a connection of MED28 and EMT in human breast cancer cells; we therefore asked whether calcitriol may also affect MED28 and EMT in colorectal cancer." (PMID 36072467, 2022). "Finally, DEPDC1 and MED28 interact with ZNF224 in bladder and breast cancer cells, respectively, and elicit two different pathways involved in the promotion and progression of tumors in two distinctive cellular milieus." (PMID 34684876, 2021).
breast carcinoma (continued). "Functionally, although no target genes of the ZNF224/MED28 complex have yet been identified, Cho and colleagues provided evidence that the interaction of ZNF224 and MED28 prevents ZNF224 degradation following DNA damage and consequently enhances the proliferation and survival of breast cancer cells." (PMID 34684876, 2021).
colorectal cancer (3 papers, 2021 to 2022). A primary or metastatic malignant neoplasm that affects the colon or rectum. "Considering MED28 as a subunit of the Mediator complex and a link with Wnt/β-catenin signaling, it is intuitive to propose MED28 as a central player involved in the effect of calcitriol on the development of colorectal cancer." (PMID 36072467, 2022). "In an earlier study, we reported that MED28 appears to regulate Wnt/β-catenin signaling and cell growth in human colorectal cancer cells." (PMID 36072467, 2022). "Together, our data support that MED28 plays an important role in the development of colorectal cancer and indicate that calcitriol may be translationally applicable as an adjuvant in fighting this malignancy." (PMID 36072467, 2022). "However, whether MED28 is also involved in the EMT event in colorectal cancer is unclear at present." (PMID 36072467, 2022). "Next, we employed RNAi to examine the role of MED28, and we found that suppression of MED28 mimicked the effect of calcitriol on E-cadherin, fibronectin, and Wnt/β-catenin signaling molecules in HT29 human colorectal cancer cells." (PMID 36072467, 2022). "Our data indicate that calcitriol attenuated MED28-mediated cell growth and EMT in colorectal cancer cells, reinforcing the implication of MED28 in the progression of colorectal cancer and supporting a promising, clinical application of calcitriol." (PMID 36072467, 2022). "In this study we identified a connection of MED28 with EMT and cell growth in human colorectal cancer cells such that MED28 regulates Wnt/β-catenin signaling and controls transcription factors involved in downregulating E-cadherin and upregulating mesenchymal markers such as MMP9 and fibronectin." (PMID 36072467, 2022). "Taken together, our data suggested that MED28 was involved in Wnt/β-catenin signaling and EMT, and calcitriol could inhibit the effect of MED28 on cell growth and EMT in colorectal cancer." (PMID 36072467, 2022).
Obesity (2 papers, 2020 to 2021). Accumulation of substantial excess body fat. "Additional genes involved in pathways closely related to the obesity phenotype highlighted by our analysis as potential candidates that play a role in male mice susceptibility to obesity are Cckar, Sod3, Med28, and Slit2." (PMID 33143653, 2020).
prostate carcinoma (2 papers, 2019 to 2021). A carcinoma that arises from epithelial cells of the prostate gland. "MED28 is highly expressed in breast, colon, and prostate cancers, and MED28 induces cancer cell proliferation via the mitogen-activated protein kinase kinase-1 (MAP2K1) signaling pathway." (PMID 30970566, 2019).
bladder cancer (1 paper, 2016). "By taking a closer look at the transcriptome analysis it becomes apparent that several MEDs are found to be both over- and underexpressed dependent on the cancer entity (e.g. MED28 in bladder cancer, CDK19 in kidney cancer)." (PMID 27050271, 2016). "Certain MEDs were found to be both over- and underexpressed in the same cancer entity [e.g. MED28 in bladder cancer (both 26%, n = 28/109); CDK19 in kidney cancer (overexpression 66%, n = 33/50; underexpression 32%, n = 16/50)]." (PMID 27050271, 2016).
breast tumor (1 paper, 2010). "In addition to its potential usefulness as a prognostic factor, MED28 may eventually prove useful for targeted therapy: a recent study showed that inhibition of MED28 resulted in smaller breast tumor xenografts in mice." (PMID 20584319, 2010).
cervical cancer (1 paper, 2022). A primary or metastatic malignant neoplasm involving the cervix. "In addition, we examined the mRNA expression of RNF4, OCIAD1, TMED5, DHX15, MED28, and LETM1 in TMEM33 knockdown cervical cancer cells." (PMID 35832191, 2022).
ductal carcinoma in situ (1 paper, 2010). "MED28 protein expression levels were increased in ductal carcinoma in situ and invasive ductal carcinoma of the breast compared to non-malignant glandular and ductal epithelium." (PMID 20584319, 2010).
invasive breast carcinoma (1 paper, 2010). A carcinoma that infiltrates the breast parenchyma. "MED28 levels were increased in DCIS lesions as well as invasive breast cancer compared to morphologically normal breast epithelium." (PMID 20584319, 2010).
invasive ductal carcinoma of the breast (1 paper, 2010). "In contrast, MED28 expression in DCIS and invasive ductal carcinoma lesions was approximately three-fold higher than either normal or DH levels (P < 0.0001)." (PMID 20584319, 2010).
lymphoma (1 paper, 2016). A malignant (clonal) proliferation of B- lymphocytes or T- lymphocytes which involves the lymph nodes, bone marrow and/or extranodal sites. "Lymphoma was found as the only tumor entity to solely show underexpression of its Mediator subunits (most strongly MED28, MED14, MED13, CDK19, all with a frequency of 100%, n = 11/11)." (PMID 27050271, 2016).
cancer (11 papers, 2010 to 2023). A tumor composed of atypical neoplastic, often pleomorphic cells that invade other tissues. "Recent studies indicate that the overexpression of MED28 induces cancer cell proliferation and increases the colony-forming ability of cancer cells upon DNA damage." (PMID 30970566, 2019). "The mammalian mediator complex subunit 28 (MED28) is overexpressed in a variety of cancers and it regulates cell migration/invasion and epithelial-mesenchymal transition." (PMID 30970566, 2019). "Recently, we reported that the interplay between MED28 and ZNF224, a Krüppel-associated-box-containing zinc finger protein transcriptional cofactor, was associated with cancer cell proliferation upon initiation of the DNA damage response." (PMID 30970566, 2019). "Moreover, the TMEM33 expression level was remarkably positively correlated with similar genes of RNF4, OCIAD1, TMED5, DHX15, MED28 and LETM1, which have been reported to be implicated in tumorigenesis of various cancers." (PMID 35832191, 2022). "In addition, the analyses of RNA-seq data from various cancers suggest that the gene amplification of MED28 closely correlates with an increase in MED28 mRNA expression." (PMID 30970566, 2019). "MED28 was also connected with cancer behavior and migration of cancer cells." (PMID 28603670, 2017).
tumor (4 papers, 2008 to 2016). "MED28 has also been associated with tumor progression in in vitro and in vivo models." (PMID 20584319, 2010). "We previously identified the Mediator subunit, MED28, as a cytosolic binding partner of merlin, the Neurofibromatosis 2 (NF2) tumor suppressor, and thus MED28 is distinct in having a cytosolic role as an NF2 interacting protein as well as a nuclear role as a Mediator complex subunit." (PMID 26445504, 2015). "MED28 is a 178 amino acid, ~24 kDa protein that was first identified as being differentially expressed in endothelial cells exposed to conditioned media from tumor cells." (PMID 20584319, 2010). "In addition, MED28 has been found to be a binding partner for merlin, a cytoskeleton-related tumor suppressor important in neurofibromatosis 2 development." (PMID 20584319, 2010).
infection (2 papers, 2015 to 2022). The state of being infected such as from the introduction of a foreign agent such as serum, vaccine, antigenic substance or organism. "To test the effects of Med28 loss on reprogramming, we carried out Med28fl/fl MEF reprogramming as above with additional infection of Ad-Cre or Ad-empty control virus." (PMID 26445504, 2015). "We verified Med28 deletion after Ad-Cre infection, but observed only heterozygous (Med28fl/-) or WT (Med28fl/fl) genotypes among 80 clones tested." (PMID 26445504, 2015).
MED28 also shares sentences with these, for which no sentence is quoted: lung carcinoma (2 papers); gastric cancer (1); kidney cancer (1); lung adenoma (1); mastitis (1); melanoma (1); ovarian carcinoma (1); pancreatic cancer (1); sarcoma (1); urogenital cancers (1).